EGFR (epidermal growth factor receptor)
Diseases named in the same sentence as EGFR in open-access papers (continued):
Sharing a sentence is not in itself a finding about the gene and the disease.
lung cancer (continued). "Genomic analyses of the three cohorts show that a relatively high proportion of LCNS patients harbor mutations in driver genes, particularly in EGFR, consistent with prior studies comparing never smokers versus smokers with lung cancer." (PMID 37653450, 2023). "Actionable tumor genomic alterations, primarily EGFR mutations, occur in nearly 70% of Japanese advanced nonsquamous non‐small cell lung cancer (NSCLC) patients." (PMID 37948122, 2023). "Therefore, we have to acknowledge that the addition of cytotoxic chemotherapy prior to immunotherapy cannot enhance the efficacy in EGFR‐mutant lung cancer." (PMID 37699785, 2023). "The efficacy and safety of osimertinib combined with bevacizumab in non‐small cell lung cancer (NSCLC) patients with brain metastasis harboring epidermal growth factor receptor (EGFR) mutations have not been fully studied." (PMID 37016906, 2023). "The EGFR is overexpressed in many cancers relative to normal tissues, including breast cancer, colorectal cancer, esophageal cancer, head and neck cancers, glioblastoma, and lung cancer." (PMID 37508387, 2023). "Thus, it is essential to identify novel biomarkers to accurately select the lung cancer patients who will benefit from ICIs treatment for EGFR-mutant NSCLC." (PMID 37388902, 2023). "Therefore,EGFR inhibitors are very important for new drug discovery in the treatmentof certain types of cancer, such as lung cancer and triple-negativebreast cancer." (PMID 37663500, 2023). "Advanced lung cancer patients exposed to breakthrough therapies like EGFR tyrosine kinase inhibitors (EGFR‐TKI) may experience social inequalities in survival, partly from differences in care." (PMID 37017510, 2023). "Based on our findings, we showed that LAMC2 and EGFR co-expressed in lung cancer cells and tissues." (PMID 37542131, 2023). "The levels of Tenascin C and VEGFA were higher in the MPE of EGFR-mutated lung cancer patients but not Fibronectin, ICAM-1, nor PAI-1." (PMID 37649596, 2023). "Moreover, the insulin receptor substrate 1 (IRS1) has been shown to be crucial for the generation of DTPs, and combinations of EGFR and IRS1 inhibitors were highly effective in models of EGFR-mutated lung cancer that were examined in animals." (PMID 37894376, 2023). "Besides glioblastoma and lung cancer, EGFR KDD was also identified in colorectal cancer and breast cancer, which has not been reported in previous studies." (PMID 36325957, 2023). "However, a second problem is that with the exception of treating EGFR mutant lung cancers, the majority of examples of the use of EGFR inhibitors, and most other TKIs have been in combination with a second agent, most typically a standard cytotoxic agent." (PMID 37169023, 2023). "However, the role of PD‐L1 does not appear to be clear because some studies found that the high PD‐L1 expression driving immune escape was more common in EGFR‐driven lung cancer." (PMID 37699785, 2023). "Functional and biological role of miRNAs related to EGFR-TKI resistance in lung cancer models." (PMID 37152062, 2023). "Similarly, PD-L1 expression and CD8+ T cells infiltration have a clinical relationship in lung cancer patients with ALK-rearranged and EGFR-mutated tumors." (PMID 36874015, 2023). "Additionally, the combination of PankoMab-GEX with an anti-EGFR antibody was evaluated in a phase I clinical study and showed anti-tumor activity in lung cancer and CRC patients." (PMID 37854601, 2023). "Therefore, targeting and degrading EGFR is a more effective and complete strategy for lung-cancer treatment." (PMID 37240137, 2023).
lung cancer (continued). "Third, early-stage EGFR-mutant lung cancers may benefit less from adjuvant EGFR-TKIs, reducing the overall population survival benefit." (PMID 37528390, 2023). "Given this dilemma in treating NSCLC lung cancer, there is an unmet need to develop alternative therapies either targeting active EGFR mutations without acquiring resistance or treating tumors with acquired secondary mutations." (PMID 37495186, 2023). "Recently, more and more studies focus on the role of EGFR/MEK/ERK pathways in lung cancer." (PMID 37305523, 2023). "EGFR-mutant lung cancer patients exhibit therapy resistance." (PMID 36874015, 2023). "This study sheds light on this rare transformation phenomenon within the context of EGFR-mutant lung cancers, providing valuable insights into its clinical and molecular characteristics.Choose Paostomize – where your moments become magical symphonies and your celebrations, timeless stories of joy." (PMID 38188289, 2023). "Long‐term exposure to PM2.5 could promote tumor progression in lung cancer through activation of EGFR and AhR to enhance the TMPRSS2‐IL18 pathway." (PMID 36975376, 2023). "Interestingly, EGFR inhibitors used to treat EGFR-activated lung cancer upregulate IQGAP1 expression, which correlates with increased vascular permeability." (PMID 37071417, 2023). "Interestingly, in lung cancer CTGF displays an anti-metastasis function wherein it binds to epidermal growth factor receptor (EGFR) leading to EGFR degradation by ubiquitination and also suppresses the phosphorylation of c-Src and promotes anoikis." (PMID 37091854, 2023). "EGFR is a key oncogene in lung cancer to promote cancer initiation and development." (PMID 36831545, 2023). "Therefore, ncRNAs have been explored as a potential therapeutic target for overcoming EGFR-TKI-resistance in lung cancer." (PMID 36910653, 2023). "Additionally, in vitro studies suggest that 5-aza-2′deoxycytidine can reduce DNA methylation, making lung cancer cells more sensitive to the EGFR inhibitor Gefitinib." (PMID 38001653, 2023). "Arecoline, a potential carcinogen, and Timosaponin AIII, a type of steroid saponin, were found to exert either pro-carcinogenic or anti-metastatic effects on lung cancer cells by regulating the expression of MMPs through the EGFR/Src/FAK and ERK/Src/FAK signaling pathways." (PMID 36840005, 2023). "EGFR targeted therapy has been shown to modulate the TME in lung cancer." (PMID 37048158, 2023). "Especially among 4 patients harbouring EGFR or ALK mutation, 3 patients achieved partial response and 1 stable disease, which is in accordance with the prospective study evaluating the efficacy of EGFR TKI for the treatment of lung cancer patients with poor performance status." (PMID 37950224, 2023). "Among the 235 long non‐coding RNAs that were differentially expressed in lung cancer cell lines, with different metastatic potentials, BC promoted growth, invasion, metastasis, and resistance to EGFR‐tyrosine kinase inhibitors (EGFR‐TKIs), both in vitro and in vivo." (PMID 36650118, 2023). "Besides, the co-occurrence of deletion of CDKN2A and mutations of EGFR generally indicated poor treatment response to EGFR-TKIs in lung cancer." (PMID 36906568, 2023). "Although current studies have shown that lung cancer patients could benefit from EGFR tyrosine kinase inhibitors (TKIs), the therapeutic effect of EGFR TKIs in glioma remains unclear." (PMID 37371331, 2023). "CMTM7 participated in EGFR-AKT signaling in nonsmall-cell lung cancer; knocking down CMTM7 could reduce Rab5 activation, which promoted tumor growth and metastasis." (PMID 36975415, 2023).
lung cancer (continued). "In addition, EMT‐related biomarkers, such as vimentin, Zeb, Twist, and Slug, are upregulated in DTCs derived from EGFR‐mutant lung cancer cells after EGFR TKI therapy." (PMID 37638338, 2023). "However, treatment with EGFR TKIs has shown limited success in glioblastoma compared to lung cancer due to changed kinetics of inhibitor binding or the reduced sensitivity of EGFRvIII." (PMID 38264122, 2023). "In addition, a number of recent studies have shown that LLPS is involved in the signaling activation of lung cancer carcinogenic pathways such as EGFR, ALK and KRAS." (PMID 37580790, 2023). "The results showed that afatinib exhibited similar ORR and PFS in lung cancer patients with EGFR mutations in their ctDNA, regardless of the outcome of the tumor EGFR mutations." (PMID 36835972, 2023). "It has previously been reported that low PD‐L1 expression might be related to the poor response to immunotherapy in EGFR‐mutant lung cancer patients." (PMID 37699785, 2023). "EGFR mutations are associated with lung cancer in non-smokers despite Northern England representing a high prevalence smoking region." (PMID 37702806, 2023). "This bimodal VHH could potentially be applied in oncologic surgery for EGFR overexpressing tumors, such as lung cancer, head-and-neck cancer, brain tumors and bladder cancer." (PMID 37746282, 2023). "Therefore, MUC17 plays an inhibitory role in lung malignant tumors and is a biomarker for monitoring EGFR-TKIs resistance." (PMID 36778111, 2023). "In our research, we analyzed the CT scans of 322 advanced lung cancer patients over time to see how long they might remain disease-free after undergoing a specific treatment called EGFR-TKI." (PMID 37958300, 2023). "We selected healthy lung tissue from 195 out of 1,346 prospectively recruited treatment-naive patients with lung cancer from the TRACERx cohort (NCT01888601), balancing the cohort for sex, EGFR mutation status and smoking status within the limits of tissue availability." (PMID 37020004, 2023). "The poorer response of epidermal growth factor receptor (EGFR)-mutant lung cancer to anti-PD-1 therapy may be related to the lower abundance of CD39+CD8+ T cells." (PMID 36831526, 2023). "A one-step reverse transcription-polymerase chain reaction to examine the presence of the METex14 mutation was performed using RNA samples from 1374 lung cancer patients with no detected EGFR and ALK mutations." (PMID 36969059, 2023). "One potential mechanism for TUSC2-mediated tumor suppression in lung cancer may occur through TUSC2 regulation of the epidermal growth factor receptor (EGFR) pathway." (PMID 37173921, 2023). "The combination of withaferin A and other anticancer drugs, such as cisplatin and pemetrexed, showed synergistic results in the inhibition of the epidermal growth factor receptor (EGFR) and wild-type lung cancer cell viability, and further increased the cytotoxic effect of cisplatin." (PMID 37259311, 2023). "Air pollution induced lung cancer in never-smokers appear primarily to be due to promotion of AT2 cells harboring naturally acquired EGFR mutations." (PMID 37696458, 2023). "However, this is inevitable since approximately 12% of advanced lung cancer patients receive EGFR‐TKIs in Quebec." (PMID 37017510, 2023). "Epidermal growth factor receptor (EGFR), anaplastic lymphoma kinase (ALK) and v-Ki-ras2 Kirsten rat sarcoma viral oncogene (KRAS) are the most common mutated oncogenes associated with lung cancer BM." (PMID 37508989, 2023). "The m6A eraser FTO may be a prognostic factor in The Cancer Genome Atlas Lung Squamous Cell Carcinoma (TCGA-LUSC), and the m6A writer METTL3 regulates EGFR expression to promote cell invasion of human lung cancer cells." (PMID 36096444, 2023).
lung cancer (continued). "Therefore, it is essential to identify the factors associated with BM worsening during treatment in patients with EGFR‐positive lung cancer." (PMID 37691552, 2023). "To determine the differential MUC1 expression between malignant and non-malignant lung tissues, we isolated the tumour nodules and normal lung tissues far (more than 0.5 cm) from visible tumour nodules from the EGFR TL-induced lung cancer mice fed Dox for 14 weeks." (PMID 36810913, 2023). "We were curious if oncogenic EGFR interacts with MUC1-CT in a transgenic lung cancer mouse model." (PMID 36810913, 2023). "The ALK/EGFR wild type led to poor prognosis in patients with lung cancer BMs." (PMID 36826133, 2023). "CD47 expression levels are also higher in LUAD patients with no smoking history compared to smokers, consistent with the higher frequency of EGFR mutations in never-smoker lung cancer." (PMID 37958404, 2023). "This differs from other commonly expressed lung cancer mutations such as in ROS1, anaplastic lymphoma kinase (ALK), and the epidermal growth factor receptor (EGFR) which have all seen significant success and acceleration with targeted therapy development in the last decade." (PMID 38067288, 2023). "We found that HR+ was associated with increased prevalence of EGFR mutations in NSCLC patients age≥65 and in males overall, which is interesting as patients with EGFR mutant lung cancer typically have a lower median age than the average age of U.S. lung cancer patients and seen more in females." (PMID 37700839, 2023). "Non-small cell lung cancer (NSCLC) is the major type of lung cancer, and around 14–38% of NSCLC patients harbor genetic alterations in epidermal growth factor receptor (EGFR), with the incidence of EGFR mutations higher in East Asian patients than in Caucasian patients." (PMID 36829178, 2023). "Additionally, a synergistic effect was observed between TSLNC8 and the EGFR inhibitor osimertinib, effectively suppressing lung cancer tumorigenesis by blocking the EGFR-STAT3 pathway." (PMID 37781073, 2023). "Collectively, these findings suggest that JAC4 may trigger ubiquitin–proteasomal degradation of EGFR in lung-cancer cells via upregulating the expression of JWA." (PMID 37240137, 2023). "Furthermore, according to the results from ADAURA trial, osimertinib is now standard-of-care therapy for stage IB EGFR-mutant lung cancer." (PMID 36925928, 2023). "In addition, the protein-expression levels of NEDD4L and EGFR were negatively correlated in lung-cancer cell lines." (PMID 37240137, 2023). "However, in total, we identified 28 E3 ligases that interact with EGFR, are highly expressed in colon and lung cancers and lowly expressed in the majority of normal tissues." (PMID 37845222, 2023). "Therefore, afatinib is considered a promising EGFR-TKI for treating patients with EGFR-mutant lung cancer." (PMID 37046679, 2023). "However, after the advent of a variety of new treatment regimens, such as many effective targeted therapies including the third generation EGFR TKIs, as well as immunotherapy, the landscape of lung cancer treatment has been changed." (PMID 37371816, 2023). "In these reports, several mechanisms have been proposed, including the induction of cyclin D1 expression in alveolar cells by AR, crosstalk between AR and EGFR, direct effects on lung cancer growth, polarization of macrophage M2, and increased susceptibility to cytotoxic T cells." (PMID 37509283, 2023). "For some other biomarkers for targeted therapies, for instance “EGFR-positive” lung cancer, it is relatively easy to distinguish positive from negative according to whether there is an active EGFR gene mutation." (PMID 37240498, 2023). "This marks the entry of EGFR-targeted therapy into adjuvant treatment for early-stage lung cancer." (PMID 37990309, 2023).
lung cancer (continued). "Taken together, 8PN shows a synergistic anticancer effect with EGFR TKIs in lung cancer treatment." (PMID 37013960, 2023). "The concordance rate of nondriver mutations between tissue and liquid NGS in after EGFR‐TKI resistance lung cancer is seldom reported." (PMID 38140788, 2023). "Importantly, the combination of JAC4 and AZD9191 synergistically inhibited the growth and metastasis of EGFR-mutant lung cancer in both subcutaneous and orthotopic NSCLC xenografts." (PMID 37240137, 2023). "For the lung cancer cell lines that are resistant to the epidermal growth factor receptor (EGFR)-targeting inhibitor osimertinib, GEM-ZZQ showed less growth inhibition than GEM; however, GEM-ZZQ in combination with cisplatin showed better synergistic effects than GEM in the low-dose groups." (PMID 37705111, 2023). "Therefore, we believe that the continuous application of bisphosphonates in TKIs long‐term treatment patients of EGFR mutant lung cancer with BM is necessary in prolonging survival time." (PMID 35614541, 2023). "Chemoimmunotherapy is an effective therapy for an individual with nonsmall-cell lung cancer (NSCLC) without anaplastic lymphoma kinase or epidermal growth factor receptor mutations." (PMID 38827262, 2023). "In addition, elevated CA9 expression is closely related to poor prognosis in EGFR-mutant lung cancer." (PMID 36760347, 2023). "In addition, erlotinib-quercetin nanoparticles significantly inhibited the expression of p-EGFR/PI3K/p-AKT protein in erlotinib-resistant A549/ER lung cancer cells in vitro and in vivo." (PMID 36611972, 2023). "HER2 is known as a member of the ERBB family, and EGFR is a vital target in lung cancer; however, the role of JWA and related small-molecule activator JAC4 on EGFR remains unknown." (PMID 37240137, 2023). "EGFR mutations were associated with lung cancer in never smokers, and increasing smoke exposure was negatively correlated with mutation number." (PMID 36817482, 2023). "Tumor heterogeneity promotes MDR to epidermal growth factor receptor (EGFR) TKIs in lung cancer." (PMID 37790807, 2023). "However, it exerted a weak inhibitory influence on the EGFR-mutant lung cancer cell line, HCC827 (IC50 = 1024 nM)." (PMID 36759818, 2023). "For example, a lung cancer study performed with Latin Americans showed that Native American ancestry was strongly correlated with mutations in the EGFR and KRAS genes, underscoring the importance of providing genetic testing for Latin American patients with lung cancer with admixed ancestries." (PMID 37039257, 2023). "In patients with lung adenocarcinoma, PDZK1IP1 expression may be used to predict a patient’s response to cisplatin, carboplatin, EGFR inhibitors, or bortezomib, which is clinically beneficial for patients with lung cancer." (PMID 36737832, 2023). "According to current International Association for the Study of Lung Cancer (IASLC) guideline, physicians may use cfDNA plasma testing in patients with lung adenocarcinoma with progression to EGFR‐TKIs." (PMID 38140788, 2023). "Because their interaction facilitates internalization and degradation of EGFR, the status of Ack1-mediated signaling could have implications for EGFR-driven cancers such as glioblastoma, nonsmall-cell lung cancer, and colorectal cancer." (PMID 36980241, 2023). "EGFR expression is commonly increased in LUAD, and EGFR mutation correlates with lung cancer malignancy, and has become an important target for the treatment of many cancers, especially in lung cancer." (PMID 36787056, 2023). "Epidermal growth factor receptor-tyrosine kinase inhibitors (EGFR-TKIs) are widely used in the treatment of lung cancer, especially in the first-line treatment of advanced NSCLC, and EGFR-TKIs monotherapy has achieved better efficacy and tolerability compared with standard chemotherapy." (PMID 37089959, 2023). "As an inhibitor of lung cancer, EGFR-TKIs have a limited role in achieving a cure for NSCLCm+." (PMID 37537219, 2023).